GBP4 (guanylate binding protein 4)
Diseases named in the same sentence as GBP4 in open-access papers (continued):
Sharing a sentence is not in itself a finding about the gene and the disease.
infection (20 papers, 2009 to 2025). The state of being infected such as from the introduction of a foreign agent such as serum, vaccine, antigenic substance or organism. "Increased expression of IRF4 and GBP4, which is associated with hypomethylation, could push TI calves towards T cell exhaustion and an inability to appropriately respond to infection." (PMID 40316897, 2025). "So, we next infected Gbp4-deficient fish with WT ST and found an increased susceptibility to the infection compared with their control siblings and impaired caspase-1 activity in response to the infection." (PMID 27363812, 2016). "Gbp4 expression has been previously observed in macrophages and dendritic cells following infection with Sendai virus or upon IFN-γ stimulation." (PMID 40607809, 2025). "This analysis revealed a significantly higher expression of Gbp4 in the OB compared to the other regions following infection." (PMID 40607809, 2025). "Interferon-induced transmembrane protein 3 (IFITM3) and guanylate-binding proteins 1 and 4 (GBP1 and GBP4) show minimal expression in controls but are significantly upregulated in the moderate infection, indicating a strong antiviral response." (PMID 39928675, 2025). "Here, to explore the early markers of ECM in the OB, we performed transcriptome analysis at early and late stages of ECM and identified Gbp4 and Irgb6 as early genes induced as early as day 3 after infection." (PMID 40607809, 2025). "Consistent with reduced IFNγ expression, the mRNA induction of Nos2, Gbp1, Gbp2, Gbp4, Gbp5, Ido1 and Acod1 was severely impaired in the spleens of Myd88−/− mice after intraperitoneal infection." (PMID 36479617, 2023). "For instance, BECs expressed increased Gbp4 and Gbp2, and LECs expressed increased Gbp4, Gbp2, and Gbp7 upon infection." (PMID 35789215, 2022). "The stimulatory effect of IFNT on RSAD2, IFIT3 and MX1 was inhibited to a greater extent by HO infection and only HO inhibited GBP4 and HERC5 expression." (PMID 33898551, 2021). "Another important difference between Caiap and Gbp4 is that forced ubiquitously expression of Gbp4 results in increased larval resistance to the infection, while Caiap overexpression barely increases infection resistance." (PMID 29123523, 2017). "More interestingly, forced expression of Gbp4 RNA alone increased resistance to the infection, caspase-1 activity and ST clearance, confirming the specificity of the MO and revealing the crucial role of Gbp4 in the resistance to this infection." (PMID 27363812, 2016). "Genetic depletion of Asc in zebrafish had no apparent effects on larval development but drastically increased the susceptibility of larvae to ST and, strikingly, completely abrogated the Gbp4-mediated increased infection resistance." (PMID 27363812, 2016). "The results showed that Cxcr2 deficiency resulted in higher susceptibility to the infection and, interestingly, it fully overcame both Gbp4- and Asc- induced infection resistance and caspase-1 activity." (PMID 27363812, 2016). "We found that both Gbp4 and Irgb6 were induced across all sorted populations, including brain-resident microglia and endothelial cells, as well as T cells and monocytes, the majority of which infiltrate the OB after PbA infection." (PMID 40607809, 2025). "Interestingly, another Gbp gene cluster (Gbp4/Gbp6/Gbp9) remained in the B compartment before and after infection, but their compartment values increased post-infection." (PMID 40539063, 2025). "In addition, infection with ST had negligible effects in the mRNA levels of Gbp4 in both neutrophils and macrophages, while both cells showed increased mRNA levels of il1b on infection." (PMID 27363812, 2016). "We then tested the impact of a Gbp4 mutant devoid of its CARD (Gbp4ΔCARD) and observed that although it was able to partially rescue the higher susceptibility of Gbp4-deficient larvae, it failed to increase their infection resistance when expressed alone." (PMID 27363812, 2016).
infection (continued). "Forced expression of granulocyte colony-stimulating factor a (Gcsfa, also known as Csf3a), drastically increased the resistance of WT larvae to ST infection, whereas it failed to rescue the high susceptibility to ST of their Gbp4-deficient siblings." (PMID 27363812, 2016). "Hence, while inflammasome-independent LTB4 biosynthesis is first required for neutrophil recruitment to the infection site, Gbp4 inflammasome-dependent production of PGD2 mediates bacterial clearance by these cells." (PMID 27363812, 2016). "Alternatively, Gbp4 may directly sense ST infection and activates Caspa through the adaptor protein Asc." (PMID 27363812, 2016). "Using this model, we uncovered a previously unappreciated role of neutrophils in the clearance of bacterial infection in vivo through the Gbp4/Asc inflammasome-dependent biosynthesis of PGs and the requirement of two independent waves of eicosanoid biosynthesis for infection clearance." (PMID 27363812, 2016). "In addition to Gbp4 and Irgb6, other genes were also upregulated by day 3 post-PbA infection." (PMID 40607809, 2025). "However, pharmacological inhibition of PG production, that is, inhibition of Ptgs1 and 2 or specifically Ptgs2, fully reversed the higher infection resistance of larvae forced to express Gbp4 but, unexpectedly, the resistance of larvae forced to express Asc was unaffected." (PMID 27363812, 2016). "As a result, we have focused on four down-regulated and immune-related proteins including STAT1, GBP4, IFIT3 and DDX58 after tachyzoite infection." (PMID 37721957, 2023). "In the presence of HO infection, the stimulatory effect of IFNT on expression of GBP4, ISG15, HERC5, RSAD2, IFIH1, IFIT3, and MX1 was significantly reduced (IFNT vs. IFNT+HO, P < 0.05–0.01)." (PMID 33898551, 2021). "Infection with either HO or KY alone had similar inhibitory effects on most ISGs (ISG15, GBP4, HERC5, RSAD2, DDX58, and IFIT3), although a slightly greater inhibitory effect of HO was observed on IFI27 and MX1." (PMID 33898551, 2021). "Guanylate binding protein 4 (GBP4) and GBP1 were both induced following GII.4 infection of both organoid lines." (PMID 32184238, 2020). "Finally, heightened induction of Gbp2, Gbp4, Gbp5, Gbp6, and Ip10 in Sts−/− cells relative to wild type cells was observed following both IFNγ treatment alone and LVS infection of IFNγ‐treated cells." (PMID 32841534, 2020). "Conversely, forced expression of Asc strongly increased larval resistance to the infection and caspase-1 activity, these effects being largely independent of Gbp4." (PMID 27363812, 2016). "Finally, we demonstrate that neutrophils are recruited to the infection site through the inflammasome-independent production of CXCL8 and LTB4 where they then mediate bacterial clearance through the Gbp4 inflammasome-dependent biosynthesis of PGs." (PMID 27363812, 2016). "More importantly, infection resulted in increased Pla2 activity in whole larvae, being this activation impaired by pharmacological inhibition of caspase-1 and, conversely, further increased by forced expression of Gbp4 and Caspa but not Asc." (PMID 27363812, 2016). "Mechanistically, neutrophils are recruited to the infection site through the inflammasome-independent production of the chemokine (CXC motif) ligand 8 and leukotriene B4, and then mediate bacterial clearance through the Gbp4 inflammasome-dependent biosynthesis of prostaglandin D2." (PMID 27363812, 2016). "Importantly, pharmacological inhibition of PG synthesis only affected the infection resistance of larvae forced to express Gbp4 but not of those forced to express Asc." (PMID 27363812, 2016). "Similar to infection with S. flexneri, expression of WT, but not catalytically inactive IpaH9.8, drastically reduced levels of GBP1, GBP2, and GBP4, but not GBP3." (PMID 29024643, 2017).
cancer (14 papers, 2012 to 2026). A tumor composed of atypical neoplastic, often pleomorphic cells that invade other tissues. "In fact, GBP1 and GBP4 were associated with a favorable prognosis in 4 types of cancer (CRC, SKCM, BC, and STC) according to the Pathology Atlas analysis." (PMID 32265897, 2020). "First, a comprehensive pan-cancer analysis was conducted, focusing on GBP4’s expression patterns and immunological functions." (PMID 38347243, 2024). "GBP4 was also found to be highly expressed in multiple cancer types, including melanoma and colorectal cancer." (PMID 38347243, 2024). "Pan-cancer analysis revealed that GBP4 plays a positive role in most cancer types via the majority of immunomodulators." (PMID 38347243, 2024). "GBP4 holds potential as a robust pan-cancer biomarker for assessing the immunological characteristics of tumors, with particular relevance to its ability to predict therapeutic responses, notably in the context of anti-EGFR therapy and immunotherapy." (PMID 38347243, 2024). "We discovered that GBP4 was positively correlated with these immune checkpoint genes in pan-cancer, and a significant correlation was observed in NSCLC." (PMID 38347243, 2024). "In conclusion, GBP4 is a pan-cancer biomarker that can be used to identify immunogenicity in human cancers." (PMID 38347243, 2024). "The results revealed that GBP4 plays a positive role with the majority of immunomodulators in most cancer types." (PMID 38347243, 2024). "First, a comprehensive analysis was conducted to evaluate the expression and prognostic significance of GBP4 in pan-cancer." (PMID 38347243, 2024). "GBP4 expression profiles offer a promising avenue for identifying highly immunogenic tumors across a wide spectrum of cancers." (PMID 38347243, 2024). "GBP4 methylation was high in cancer tissues in EC, which indicated that GBP4 was a favorable biomarker in EC." (PMID 33350104, 2021). "It is worth to note that all these genes except GBP4, are reported to have a direct or indirect influence on immune cell infiltration, and some of them have been used as prognostic marker in different cancers." (PMID 34040608, 2021). "Similarly, GBP4, an interferon- and cytokine-induced gene, has been recognized for its functional relevance in various human cancers." (PMID 40362379, 2025). "Using the TIMER database, we discovered that GBP4 expression was inconsistent in most cancers." (PMID 38347243, 2024). "In addition, we also conducted a pan-cancer analysis and found that GBP4 was positively correlated with the inflamed TIME, and the positive correlation between GBP4 and PD-L1 was validated in multiple in-house cohorts." (PMID 38347243, 2024). "In this study, a pan-cancer analysis of the expression and immunological characteristics of GBP4 was conducted, and the results revealed that GBP4 was strongly correlated with immunological factors in most cancers, especially non-small cell lung cancer (NSCLC)." (PMID 38347243, 2024). "Moreover, the results of the pan-cancer analysis suggest that GBP4 can be used to predict high immunogenicity in most cancers." (PMID 38347243, 2024). "While the role of GBP4 in cancer has been preliminarily summarized, its correlation with antitumor immunity remains unclear and requires further research." (PMID 38347243, 2024). "However, the prognostic value of GBP4 was limited in human cancers." (PMID 38347243, 2024). "GBP4 mRNA is expressed at a low level in LUAD and LUSC but is expressed at a high level in several other cancer types." (PMID 38347243, 2024). "Guanylate binding protein 4 (GBP4) is induced by interferons and various cytokines and has been recognized as functionally relevant in numerous types of human cancers." (PMID 38347243, 2024). "Furthermore, we assessed the correlations between GBP4 and immune checkpoint genes, including TIGIT, CTLA4, CD274 and PDCD1, across cancers." (PMID 38347243, 2024). "Among all these 5 DNA, GBP4, GABRA2, and RIPPLY2 were once reported in cancer research." (PMID 33350104, 2021).
cancer (continued). "Gene set enrichment analysis (GSEA) of cancer hallmarks pathways in neutrophils showed upregulation of IFN-γ response genes in Group 1 compared with Group 2, which is confirmed by higher expression of IFN-γ–inducible guanylate binding proteins (Gbp2, Gbp4, Gbp6, and Gbp7)." (PMID 41165751, 2026). "MF HSC/MPP showed a high expression of immune and inflammatory pathways (HLA genes, GBP4, and IFITM1), a matrix- and collagen-degrading enzyme (MMP2), and genes with oncogenic function (MYCN, KRT8, and KRT18) that have been correlated with cancer progression and poor survival." (PMID 34525349, 2021).
bacterial infections (2 papers, 2016 to 2025). "However, considering the established role of IFN-inducible GTPases in host immune defence, especially against toxoplasma and bacterial infections, we suspect that Gbp4 and Irgb6 may have a more significant impact on APCs, including endothelial cells." (PMID 40607809, 2025). "The increased bacterial resistance of fish forced to express Gbp4, Asc or Caspa with no apparent side effects suggest that transient activation of the inflammasome may be beneficial in certain bacterial infectious diseases." (PMID 27363812, 2016).
GBP4 also shares sentences with these, for which no sentence is quoted: colon carcinoma (2 papers); ovarian carcinoma (2); tuberculosis (2); childhood asthma (1); glioblastoma (1); glioma (1); H1N1 virus infection (1); Hepatitis (1); infectious disease (1); liver cancer (1); lymphoma (1); malaria (1); measles (1); non-small cell lung carcinoma (1); oropharyngeal squamous cell carcinoma (1); rheumatoid arthritis (1); sarcoidosis (1); squamous cell carcinoma (1); stomach cancer (1).